POM121C (POM121 transmembrane nucleoporin C)
Description:
Essential component of the nuclear pore complex (NPC). The repeat-containing domain may be involved in anchoring components of the pore complex to the pore membrane. When overexpressed in cells induces the formation of cytoplasmic annulate lamellae (AL).
Synonyms: POM121-2
Tractability: Antibody: UniProt predicts a signal peptide or a membrane-spanning region. PROTAC: ubiquitination databases record sites on it; its protein half-life has been measured.
Gene: Protein-coding gene on chromosome 7 (75,416,784 to 75,486,358, reverse strand). Ensembl gene ENSG00000272391.
Subcellular location: Nucleus, nuclear pore complex; Nucleus membrane; Endoplasmic reticulum membrane
Subcellular location (Human Protein Atlas): Nuclear membrane; Nucleoplasm
Pathways (Reactome):
Disease: Defective TPR may confer susceptibility towards thyroid papillary carcinoma (TPC); HCMV Early Events; HCMV Late Events; NEP/NS2 Interacts with the Cellular Export Machinery; NS1 Mediated Effects on Host Pathways; Nuclear import of Rev protein; Rev-mediated nuclear export of HIV RNA; SARS-CoV-2 activates/modulates innate and adaptive immune responses; Transport of Ribonucleoproteins into the Host Nucleus; Viral Messenger RNA Synthesis; Vpr-mediated nuclear import of PICs
Metabolism of RNA: Transport of Mature mRNA Derived from an Intronless Transcript; Transport of Mature mRNA derived from an Intron-Containing Transcript; Transport of the SLBP Dependant Mature mRNA; Transport of the SLBP independent Mature mRNA; snRNP Assembly; tRNA processing in the nucleus
Metabolism of proteins: SUMOylation of DNA damage response and repair proteins; SUMOylation of DNA replication proteins; SUMOylation of RNA binding proteins; SUMOylation of SUMOylation proteins; SUMOylation of chromatin organization proteins; SUMOylation of ubiquitinylation proteins
Metabolism: IP3 and IP4 transport between cytosol and nucleus; IP6 and IP7 transport between cytosol and nucleus; IPs transport between nucleus and cytosol; Regulation of Glucokinase by Glucokinase Regulatory Protein
Cell Cycle: Nuclear Pore Complex (NPC) Disassembly
Cellular responses to stimuli: Regulation of HSF1-mediated heat shock response
Immune System: ISG15 antiviral mechanism
Gene Ontology:
Molecular function: protein binding; structural constituent of nuclear pore
Biological process: protein import into nucleus; RNA export from nucleus
Cellular component: nuclear envelope; nuclear pore; endoplasmic reticulum membrane; nuclear membrane
Genetic constraint (gnomAD): Loss-of-function variants: 20 observed, 53.54 expected, observed/expected ratio (o/e) 0.37, 90% interval 0.26 to 0.54. The synonymous counts are far from expectation, so gnomAD's model fits this gene poorly and the ratio says little. Missense variants: 564 observed, 924.75 expected, observed/expected ratio (o/e) 0.61, 90% interval 0.57 to 0.65. Synonymous variants: 279 observed, 370.14 expected, observed/expected ratio (o/e) 0.75, 90% interval 0.68 to 0.83.
Homologues: Orthologues: chimpanzee POM121 (95% identical), macaque POM121C (94% identical), dog POM121C (72% identical), mouse Pom121 (68% identical), rat Pom121 (68% identical), zebrafish pom121 (33% identical), tropical clawed frog pom121 (23% identical), Drosophila melanogaster Nup153 (15% identical). Paralogues in human: POM121 (97% identical), POM121L2 (41% identical), NUP214 (26% identical), NPAP1 (22% identical), NUP153 (21% identical), POM121L12 (5% identical).
Diseases named in the same sentence as POM121C in open-access papers:
POM121C is named in the same sentence as 4 diseases in open-access papers, as found by Europe PMC text mining. Sharing a sentence is not in itself a finding about the gene and the disease. The quoted sentences say what the papers report.
breast carcinoma (1 paper, 2017). "Among these, 11 CNVRs overlapped with 12 genes (GSTM2, RAB40B, HLA_DRB5, HLA_DRB6, EYA1, DOCK3, ANKS1B, CACNA1C, RAB11FIP3, BAGE, SGCZ, POM121c) and were specifically associated with breast cancer risk and OS." (PMID 29116104, 2017).
diabetics (1 paper, 2023). "In particular, beta cells of diabetics exhibited decreased expression of genes encoding molecular chaperones belonging to the heat shock families Hsp70 (HSPA1B, HSPA7, and HSPA8) and Hsp90 (HSP90AA1 and HSP90AB1) as well as co-chaperones (BAG3 and ST13) and nucleoporins (NDC1, NUP160, and POM121C)." (PMID 37569434, 2023).
POM121C also shares sentences with these, for which no sentence is quoted: endometriosis (1 paper); melanoma (1).